IL15 (interleukin 15)
Diseases named in the same sentence as IL15 in open-access papers (continued):
Sharing a sentence is not in itself a finding about the gene and the disease.
viral infection (continued). "Up on viral infection macrophages have been shown to produce cytokines like IL-15, TNF-α and IL-12." (PMID 26085921, 2015). "Despite the role IL-15 has been show to play in protective immunity to certain viral infections and elaboration of antiviral cytokines, we were unable to detect impaired antiviral cytokine or ISG expression in our ligand stimulated γc -deficient XSCID keratinocytes." (PMID 25025687, 2014). "IL-15 has been shown to play a role in antiviral immunity, where it can mediate the release of IFNs and other antiviral cytokines as well as play an essential role in protective immunity to certain viral infections." (PMID 25025687, 2014). "We hypothesized that delivery of a highly functional and potent IL15Rα-IL15 cytokine, especially in the context of viral infection, would provide a necessary boost to immune cells in driving their functional anti-tumor activities." (PMID 25329832, 2014). "Immunotherapy using NK-enhancing cytokines like IL-15 may benefit neonates with severe viral infections." (PMID 24066005, 2013). "Following viral infections, de novo production of IL-15 by dendritic cells results in the activation and proliferation of NK cells, and transient systemic stimulation of NK cells with soluble IL-15/IL-15Rα complexes also results in an accumulation of phenotypically and functionally mature NK cells." (PMID 22624047, 2012). "Multiple studies in both human and murine models have shown that antigen‐specific CD8+ T cells derived from chronic viral infections often fail to develop into long‐lived memory cells, even after viral clearance, and lack the capacity for homeostatic proliferation in response to IL‐7 and IL‐15." (PMID 41410180, 2025). "Our current study further raises the question that whether the IL-15/NKG2D axis would contribute to bystander activation of CD8+ T cells in other human viral diseases, and whether IL-15 or NKG2D could be considered as a therapeutic target in the treatment of the immunopathology of viral diseases." (PMID 36590594, 2022). "Similarly, IL-15 induction is interferon (IFN)-α receptor (IFNAR)-dependent after viral infection." (PMID 33815365, 2021). "Interestingly, this effect of EPs 7630 treatment was also detected in non-infected cells, boosting the production of immune-regulating cytokines IL-9, IL-12, and IL-15, and potentially setting the course for a more balanced immune response towards virus infection in epithelial cells (IV.)." (PMID 34759825, 2021). "On the other hand, IL-15 priming has been demonstrated to reduce NK cell reliance on cellular metabolism, hence, IL-15 agonists may be effective for enhancing NK cell function in metabolically challenging environments, including viral infections and cancers." (PMID 32983138, 2020). "Finally, the induction of CD49a on NK cells could indicate that IL-15 plays a role in aiding establishment of tissue-residency in NK cells upon local increase in IL-15 production during viral infections, as has previously been proposed for CD8+ TRM cells." (PMID 31451696, 2019). "Hence, a coordinated availability of IL-12, IL-15, and IL-18, derived from dendritic cells and myeloid cells during viral infections such as CMV or influenza, might support generation of cytokine-induced memory-like NK cells in vivo." (PMID 30546366, 2018). "Although other inflammatory mediators may contribute to IFNγ production, we did not observe any correlation with IL-12, IL-15, or other molecules previously reported to be associated with IFNγ and/or viral infections such as IP-10, MIG, I-TAC, MCP-1, RANTES." (PMID 28830544, 2017). "Therefore, we aimed to evaluate whether poly I:C (an experimental model of viral infections) and IL-15 induce CXCL10 production in mucosal tissue." (PMID 24586509, 2014). "Even during certain viral infections IL-15 might be dispensable for NK-cell activation." (PMID 20213736, 2010).
viral infection (continued). "We also measured plasma IL-15 levels in patients with active SLE (n = 10) and acute viral infection (n = 17)." (PMID 37751296, 2023). "Similar to the data we obtained from chronic viral infection in mice, the expansion of the Tpex subset of PD-1+ CD8 TILs upon ex vivo IL-15 treatment was significantly higher than that of the terminally differentiated subset." (PMID 37409128, 2023). "As expected, HSV-1 infection induced a substantial increase in IRF-1, TNF-α, and IL-15 mRNA levels in the wild-type Vero cell line, increasing IRF-1 up to 30-fold 2 days after viral infection." (PMID 35897807, 2022). "Interleukin-15 (IL-15), another cytokine induced by IFN-γ receptor signaling, primarily functions in host defense against viral infection." (PMID 35897807, 2022). "It would be interesting to determine how IL-1β, IL-23, IL-15, and other cytokines are dynamically regulated to control MAIT cell-mediated immune protection, as well as pathogenesis during viral infections and other inflammatory conditions in the future." (PMID 33795689, 2021). "During a typical viral infection, pro-inflammatory cytokines, such as Type 1 IFN, IL-12, IL-15, and IL-18, are generally elevated, inducing NK cell blastogenesis in early virus infection." (PMID 33365027, 2020). "Both WT and CD62L-/- memory CD8+ T cells synthesized ligands for P- and E-selectin following stimulation with IL-15, which we have previously demonstrated to be essential for memory CD8+ T cell trafficking into the skin following viral infection." (PMID 30875408, 2019). "Hence, IL-15 may have a key role also for lung trNK cell activation during viral infections." (PMID 31451696, 2019). "IL-12 and IL-18 secreted during viral infections by e.g., dendritic cells induce potent NK cell IFN-γ production and cytotoxicity, in particular in combination, and synergistically augment IL-2 and IL-15–induced NK cell activation." (PMID 30546366, 2018). "Under inflammatory conditions, such as viral infection, type I IFN drives the secretion of IL-15 which subsequently favors the rapid division of memory CD8 T cells following an antigen encounter and enhances their protective capacity against viral infection." (PMID 28713392, 2017). "NK cells are activated during the initial stages of viral infections by cytokines and chemokines, including IFN-α, IFN-β, IL-12, IL-15, and IL-18, produced by infected cells or by activated dendritic cells and macrophages." (PMID 24066005, 2013). "The ability of IL-15 to activate both NK and CD8+ T cells makes it a potential effective immunotherapy for neonates with severe life-threatening viral infections." (PMID 24066005, 2013). "Down-regulation of IL15, NOS2A, CCR4 and up-regulation of IL17, CYP7A1, SELE, IL5, RPL3L genes in both patient categories indicative of response to p-H1N1-09 virus infection." (PMID 20957032, 2010). "Monitoring and management involved using enzyme-linked immunosorbent assay (ELISA) to measure interleukin 15 (IL-15) and vascular endothelial growth factor (VEGF) levels and fluorescence microscopy to observe virus infection efficiency, ensuring accurate tracking of therapeutic efficacy and safety." (PMID 39328617, 2024). "While IL-15 production is a key biological response to viral infection, this pathway was more methylated regardless of viral infection status in the mother." (PMID 37899449, 2023). "Moreover, recent studies show that NKG2AC+CD8+ T cells, which are innate-memory cells from rhCMV- or SIV-infected macaques, help to control viral infection by increasing expression of EOMES and production of IFN-γ via IL-15 stimulation." (PMID 37658106, 2023). "We demonstrate that the combination of IFN-I and IL-15 potentiates the generation of CD38+HLA-DR+ lymphocyte subsets in vitro and provide a mechanistic link between viral infections and MAS in SD that may be targetable by JAK inhibition." (PMID 37751296, 2023).
viral infection (continued). "We provided a possible mechanism of CD8+ T cells bystander activation mediated by the IL-15/NKG2D axis, which may be helpful to reveal the role of bystander-activated CD8+ T cells for the immunopathological injury during viral infection." (PMID 36590594, 2022). "Immune activation in the lung during, e.g., viral infection results in elevated levels of IL-15 in the tissue but not in the serum, as demonstrated in influenza infection models." (PMID 31451696, 2019). "In acutely infected IAV patients, serum/plasma levels of IL-6, IL-8, IL-15, and CXCL10 (IP-10) are elevated, and airway epithelial cells and alveolar macrophages release CXCL10 and IL-15 in the lung upon stimulation with IFN-γ, viral infection, or other pulmonary diseases." (PMID 31156653, 2019). "IL-15 is essential for NK cell activation, and its expression can be modulated by virus infection of non-immune cells." (PMID 25412359, 2014). "Remarkably and in sharp contrast with pNK cell response to viral infection, there were no changes in secretion levels of cytokines such IL-12, IL15, type I IFN, TNFα or IFN-γ that are all known to regulate NK cell function." (PMID 23592985, 2013). "IL-15 is important in linking innate and adaptive antiviral immune responses, promoting natural killer (NK) and memory CD8 T cell anti-viral immune responses and monocytes/macrophages produce IL-15 in response to virus infections." (PMID 21779162, 2011). "Thus, since IL-15 mimics the differential activation state of HCMV, EBV and influenza-specific CD8 detected in patients with acute viral infections, we performed a series of functional experiments using PBMC of healthy individuals activated with IL-15." (PMID 20808900, 2010). "However, it is important to stress that this causative link is hypothetical since the level of IL-15 required to activate HCMV/EBV in vitro (1–10 ng/ml) is higher than what we detected in the serum of the patients in this study (always lower then 50 pg/ml in any viral infection, data not shown)." (PMID 20808900, 2010). "Our findings demonstrating direct, IL-15-independent effects of IFNε on NK cells are consistent with reports that NK cell expression of the type I IFN receptor (IFNAR) is required to mediate their cytolytic activity and IFNγ production in other sites during viral infections." (PMID 38263527, 2024). "Interleukin-15 (IL-15) is a critical cytokine for the development, proliferation, and function of natural killer (NK) cells, NKT cells, and CD8+ memory T cells and has become one of the most promising protein molecules for the treatment of cancer and viral diseases." (PMID 34107983, 2021). "Furthermore, de novo IL-15-induced CD49a+CD16− lung NK cells were highly responsive, possibly promoting the generation and discrete activation of trNK cells in the lung upon local exposure to IL-15 during, e.g., viral infection." (PMID 31451696, 2019). "It is to be noted that in response to IL-15 augmentation upon bortezomib treatment, enhanced PI3K/Akt/STAT5 activation may support the maintenance and survival of effector and memory CD8+T cells as observed during viral infections." (PMID 28052005, 2017). "It is also possible that this finding is only a reflection of the timing when the naïve horses exposed to WNV were euthanized (at the onset of clinical signs) and a beneficial response from IL-15 to viral infection could not be realized in these horses." (PMID 21991302, 2011). "Thus it appears that IL-15 is upregulated in response to WNV infection, and while it may play a key role in recovery from viral infection, its dysregulation may be a key component of the immunopathology of this disease." (PMID 21991302, 2011). "This is not surprising as IL-15, in concert with IL-7, acts as a regulator of CD8+ T cells, whose primary role is in the immune response to viral infection, and not bacterial infection." (PMID 21711552, 2011).
viral infection (continued). "Furthermore, control β.anti-NKG2A without IL-15 stimulated degranulation of NK cells with additional IFN-γ expression on CD8+ T cells as well, indicating that blocking the receptor in the context of viral infection might be more effective than in the context of cancer therapy." (PMID 37936122, 2023).
leukemia (97 papers, 2013 to 2026). A malignant (clonal) hematologic disorder, involving hematopoietic stem cells and characterized by the presence of primitive or atypical myeloid or lymphoid cells in the bone marrow and the blood. "Low serum IL-15 levels immediately following allogeneic HSCT have been associated with leukemia recurrence." (PMID 39411712, 2024). "Conversely, IL-15 deficiency has been linked to leukemia development in an immunodeficient mouse model, suggesting a protective role of IL-15 against leukemia." (PMID 37153603, 2023). "Low serum levels of IL-15 in patients with leukemia early post-allo-HSCT were associated with relapse of the disease." (PMID 35356211, 2022). "Interleukin-15 (IL-15) single-nucleotide polymorphisms and/or mRNA levels have been implicated in leukemia chemoresistance as well as likelihood of CNS disease in leukemia." (PMID 28491865, 2017). "Taking away the ATF4-mediated blockade, sorafenib allowed IRF7 activation and caused IL-15 transcription in the leukemia cells which caused an increase of CD8+ CD107a+ IFNγ+ T cells, which was connected to the increased elimination of leukemia cells by activated donor T cells." (PMID 35460465, 2022). "In addition to upregulating genes in leukemia cells implicated in CNS trafficking, IL-15 also enhances leukemia proliferation through an effect on the Raf/Ras/ERK signaling pathway." (PMID 28491865, 2017). "A study on B-ALL patients discovered that the expression levels of cytokines IL-7, IL-10 and IL-15 and their receptors were higher than those in healthy controls, suggesting the existence of a complex autocrine/paracrine mechanism underlying the regulation of leukemia cell functions." (PMID 28408741, 2017). "Their preclinical studies showed potent in vivo lysis of CD19+ leukemia cells, prolonged NK cell survival via IL-15 expression, and efficient leukemia clearance following activation of the iCasp9 switch." (PMID 41586193, 2025). "IL-15 would also have an additional effect by enhancing NK cells’ response to leukemia cells through increased activation receptors and enhanced cytolytic potential." (PMID 39273395, 2024). "Feeder cell lines, like the modified K562 leukemia cells expressing IL-15 or the recent version expressing IL-21 and 4-1BBL, offer an alternative strategy for ex vivo expansion and are considered safer for clinical application." (PMID 39339180, 2024). "The fourth-generation CAR-T cells, engineered to secrete IL7 and IL15, demonstrated high anti-leukemia activity in preclinical animal models." (PMID 38927401, 2024). "One promising area of therapy for bovine leukemia is the combination of IL-15 with immune checkpoint blockade." (PMID 39507777, 2024). "Skeletal muscle contributes to systemic effects by secreting cytokines and other myokines (including IL-6, IL-8, IL-15, and leukemia inhibitory factors) through local autocrine, paracrine, and endocrine actions." (PMID 37736552, 2023). "In a preclinical study, sorafenib was shown to promote a graft-versus-leukemia effect by inducing the secretion of T and NK cells growth factors, namely IL-15 by AML cells." (PMID 37007116, 2023). "Additional findings confirmed that IL-15 is involved in leukemia growth through an autocrine/paracrine mechanism." (PMID 37153603, 2023). "Leukemia raised in IL-15 transgenic mice has been recognized as an in vivo model of LGLL, further confirming the cytokine’s pathogenetic role in this disorder." (PMID 37153603, 2023). "Adult T-cell leukemia (ATL), a rare and aggressive leukemia associated with human T-cell lymphotropic virus type 1 (HTLV-1), was the first model that allowed the discovery of some main functions of IL-15 in cancer." (PMID 37153603, 2023). "Previous studies demonstrated that activated NK cells by IL-15 or other cytokines inhibit systemic peripheral leukemia but cannot enter CNS to control the leukemia relapse." (PMID 36941630, 2023).
leukemia (continued). "Their preclinical studies demonstrated that iC9/CAR.19/IL-15 CB NK cells efficiently killed CD19+ primary leukemia cells and Raji in vitro and significantly prolonged the survival in a xenograft Raji lymphoma murine model." (PMID 35258793, 2022). "Researchers showed that Sorafenib increased IL-15 production by FLT3-ITD leukemia cells, which in turn caused an increase in CD8+CD107a+IFN y T cells which eradicated leukemia in secondary recipients." (PMID 36530990, 2022). "IL-15 gene and an inducible caspase-9-based suicide gene emerged to generate safe iC9/CAR.19/IL-15 + T cells against lymphoma and leukemia." (PMID 36419058, 2022). "Despite the improved anti-AML efficacy of CD123-ENG.IL15 T-cells, leukemia eventually progressed in both PDX models." (PMID 35615350, 2022). "Our group and others have successfully expanded active PB NK cells or CB NK cells in vitro by co-culture with irradiated EBV-LCL, or with K562 cells expressing transfected cell-membrane bound IL-15 and 4-1BBL to kill leukemia and B-NHL." (PMID 35258793, 2022). "In one study, peripheral T cells stably expressing second-generation CD19-CAR and IL-15-IL-15Ra retarded leukemia development and sustained resistance after tumor clearance with long-lived Tscm." (PMID 36167591, 2022). "Changes in the microenvironment associated with decreased production of IL-15 and IFN-γ from myeloid cells can favor leukemia relapse, as IL-15 secretion expands and activates effector T and NK cell antileukemic responses." (PMID 35242706, 2022). "Based on preclinical data, the drug is able to increase the immunogenicity of leukaemia cells via induction of interleukin-15 production, thereby enhancing T cell activation." (PMID 33603142, 2021). "Phosphorylation of Tyr348 in GART was also reported in a human leukemia-derived T-cell line following stimulation with IL-2 or IL-15." (PMID 34283052, 2021). "Increased IL-15 has been found in many autoimmune diseases, and the transgenic overexpression of IL-15 leads to leukemia in mice." (PMID 34439192, 2021). "Another approach to maximize the anti-leukemia potential of NK cells is to pre-activate NK cells with IL-12, IL-18 and IL-15 to differentiate them into cytokine-induced memory-like NK cells." (PMID 34572387, 2021). "Remarkably, NK cells preactivated with a cocktail of cytokines (IL-12, IL-15 and IL-18) exhibited augmented anti-leukemia responses to restimulation for weeks to months regardless of inhibitory KIR-KIR ligand interactions." (PMID 33287858, 2020). "There is evidence that IL15 can promote the pathogenesis of leukemia and control the proliferation and survival of leukemic progenitors." (PMID 31740623, 2019). "In this study we have investigated the potential of interleukin-15 (IL-15) as an immunomodulator in an intraperitoneal cell-delivered leukemia mouse model." (PMID 31856922, 2019). "Here we describe the impact of intraperitoneal IL-15 in a cancer cell-delivered IL-15 immunotherapy approach using the 70Z/3-L leukemia mouse model." (PMID 31856922, 2019). "Anti-leukemia CAR T cells that express IL-15 have increased expansion, viability, and improved antitumor immunity compared to conventional CAR T cells in lymphoma xenograph models." (PMID 30842774, 2019). "In the present study we demonstrate that ip-administered IL-15-secreting leukemia cells can elicit a protective immune response in the 70Z/3-L mouse leukemia immunotherapy model." (PMID 31856922, 2019). "Deniger and colleagues demonstrated that the propagation of CD19+CD64+CD86+CD137L+IL-15+ APCs enhanced the activity of anti-CD19 CAR γδT cells against preclinical leukemia models in vivo." (PMID 31212634, 2019). "NK activation is triggered by interleukins, e.g., IL-15, the serum level of which is elevated in patients with leukemias." (PMID 30719179, 2019).